BRD4 (bromodomain containing 4)
Diseases named in the same sentence as BRD4 in open-access papers (continued):
Sharing a sentence is not in itself a finding about the gene and the disease.
melanoma (continued). "Silencing of BRD4 using two independent shRNAs (LV-shBRD4.1 and LV-shBRD4.2) strongly decreased the expression of GLI1 at both mRNA and protein level in melanoma cells." (PMID 33958721, 2021). "The results of immunohistochemistry analyses of melanoma tissues from the Human Protein Atlas indicated that BRD7, BRD9, BRD4, BRD3, and KDM6B were mostly expressed at >75% level." (PMID 34771678, 2021). "Key recent studies have shown that JQ1 treatment in melanoma and multiple myeloma cells depletes BRD2 and BRD4 from promoter and enhancer regions of the genome, and this was associated with the disruption of transcriptional programs in these cells." (PMID 32315290, 2020). "Since TYR and TYRP1 are MITF target genes, we interrogated previously published ChIP-seq datasets to determine if BRD4 and MITF co-occupy MITF-binding sites at the TYR and TYRP1 loci in melanocytes and melanoma cells." (PMID 32151278, 2020). "BRD4 is the most well studied member of the BRD family in multiple cancers, such as melanoma, MPM, CRPC, neuroblastoma and lung adenocarcinoma." (PMID 32927435, 2020). "Chromatin immunoprecipitation (ChIP) analysis highlighted the ability of these compounds to antagonise the interaction between BRD4 and chromatin at the MYC promoter in melanoma cells to effect the down regulation of oncogenic c-myc." (PMID 30909892, 2019). "We report that BET proteins are overexpressed in NRAS‐mutant melanoma, and that these tumors are dependent on the BET family member, BRD4." (PMID 29650805, 2018). "It has been demonstrated that BRD4 inhibition by JQ1 inhibits proliferation of many malignant tumors, including myeloma, melanoma, colorectal cancer, rhabdomyosarcoma and Ewing sarcoma." (PMID 28545522, 2017). "In in vitro studies, two BRD4 inhibitors (JQ1 and I-BET762) have been found to effectively inhibit the proliferation and growth of cancer cells such as melanoma, pancreatic cancer, lung cancer, multiple myeloma, acute myeloid leukemia, and Burkitt's lymphoma." (PMID 28415703, 2017). "BET family members BRD2 and BRD4 are over expressed in melanoma and are able to be inhibited by a number of relatively novel drugs such as JQ-1 and I-BET151, leading to reduced melanoma growth, cell death and reduction in NF-κB activity." (PMID 26426052, 2015). "Inhibiting BRD4, either through the BET pharmacological inhibitor JQ1 or BRD4‐specific siRNA, may prevent melanoma cell metastasis by curtailing cell invasion and migration while facilitating the phagocytosis‐mediated elimination of melanoma cells." (PMID 41546170, 2026). "Given this role of BRD4 in melanocyte biology, we hypothesized that SETD6-mediated methylation of BRD4 would modulate the transcriptional program in melanoma cells." (PMID 40809945, 2025). "However, we showed that the synergistic inhibition of BRD4 by the JQ1 inhibitor and of IRS2 by the NT157 inhibitor exerted a significant anti‐melanoma cell impact." (PMID 40285526, 2025). "In vemurafenib-resistant melanoma cells (A375R), ARNIPL showed significantly improved cytotoxic effects and reduced IC50 values compared with free drugs, indicating strong synergy through BRD4 degradation, c-Myc suppression, and increased apoptosis." (PMID 40284496, 2025). "Future work will reveal whether SETD6 and the methylation of BRD4 are also required for BRD4 and MITF transcriptional activity in regulating specific gene expression programs in melanoma." (PMID 40809945, 2025). "Here, they found that small‐molecule inhibitors of BRD4 and IRS2, in combination, mimicked the effects of the hemoglobin alpha/beta heterodimer and restricted the malignant phenotype of brain‐metastasizing melanoma cells." (PMID 40285526, 2025). "In melanoma, a previous study failed to rescue the growth-inhibitory phenotype of BRD4 deletion with MYC overexpression 33, suggesting that MYC is not the main target of BRD4 in melanoma." (PMID 38169595, 2024).
melanoma (continued). "Here, we demonstrated a strong correlation between BRD4 and YAP1 in melanoma patient samples." (PMID 38169595, 2024). "Therefore, our approach was to use ARV as a BRD4 selective PROTAC and PTEN plasmid as a tumor suppressor gene for simultaneous indirect inhibition of c-Myc expression in VEM-resistant melanoma." (PMID 39238805, 2024). "Others have shown that combination inhibition of BRD4 and ATR demonstrates synergistic cytotoxic activity in other cancers such as lymphomas, melanoma and high-grade serous ovarian cancer 58–60, however ARID1A loss as a biomarker of sensitivity was not explored." (PMID 37841875, 2023). "In conclusion, in this study we provide evidence of a novel mechanism of non-canonical SMO-independent activation of GLI1 by the SOX2-BRD4 axis and describe the efficacy of a combinatorial treatment with a novel SMO inhibitor and the PROTAC-derived BRD4 degrader MZ1 in melanoma." (PMID 33958721, 2021). "Our study found that BRD4 silencing in A375 melanoma cells did not affect the expression of transcriptional factors in the canonical NF-κB pathway but affected NFKB2 expression in the noncanonical NF-κB pathway." (PMID 33052224, 2020). "The concept of developing protein-protein interaction inhibitors to treat melanoma, however, has previously been investigated with small molecule PPI inhibitors of the complex between bromodomain-containing protein 4 (BRD4) and acetylated histone having been developed." (PMID 30909892, 2019). "Additionally, TCF19 levels positively correlated with BRD4 protein levels and sensitivity to BETi in NRAS‐mutant melanoma cells (r = −0.740, P = 0.023)." (PMID 29650805, 2018). "This analysis revealed that high BRD4 mRNA expression was associated with poor patient survival (P = 0.001) and disease‐free survival (P = 0.0008; Fig EV1) in NRAS‐mutant melanoma patients, but not in other genetic cohorts." (PMID 29650805, 2018). "Our studies have uncovered BRD4 as a key vulnerability in NRAS‐mutant melanoma and demonstrate that co‐targeting BET and MEK could be a highly efficacious strategy to treat melanoma refractory to current therapies." (PMID 29650805, 2018). "High expression of BRD4 has been reported in colorectal cancer, melanoma, metastatic breast cancer, hepatocellular carcinoma, and non-small cell lung cancer." (PMID 28415703, 2017). "Many of those, such as non-small cell lung cancer, metastatic breast cancer and melanoma do not currently have effective conventional therapies, making BRD4 inhibition a very promising option by default." (PMID 25603177, 2015). "The combination therapy of BRD4 inhibitor (JQ1) plus MEK inhibitor (PD901) synergistically downregulated the transcription factor 19 (TCF19), increased apoptosis in vivo, reduced the growth of NRAS‐mutant melanoma, and prolonged the survival of mice which resisted to MAPK inhibitors and ICIs." (PMID 41492362, 2026). "Our western blot analysis results therefore confirmed our hypothesis of targeting various cellular signaling pathways including PI3K/Akt, RAS/MAPK and BRD4 degradation to finally target c-Myc oncogene by simultaneous delivery of PL-NANO and AL-NANO in BRAFi-resistant melanoma." (PMID 39238805, 2024). "Combination of MZ1, a potent BRD4 degrader designed using the Proteolysis Targeted Chimeras (PROTACs) technology, with the SMO inhibitor MRT-92 yields a synergistic reduction of melanoma cell growth in vitro and in vivo, providing a rationale for a novel therapeutic approach in melanoma." (PMID 33958721, 2021). "For example, a recent study showed that secreted phosphoprotein 1 (SPP1) expression can be a melanoma driver, and BET inhibitor NHWD-870 targets the BRD4 subunit and suppresses SPP1 expression and ultimately melanoma progression via the non-canonical NF-κB/SPP1 pathway." (PMID 36844227, 2023).
melanoma (continued). "Silencing of BRD4, as well as its pharmacological depletion with MZ1 or catalytic inhibition through JQ1, prevented SOX2-binding to GLI1 promoter, without altering SOX2 expression in melanoma cells." (PMID 33958721, 2021). "While it was possible to obtain overlapping BRD4, BRD2, and MITF peaks on representative genes in different melanocytes and melanoma cells, we could not find BRD4, BRD2, and MITF ChIP-seq data for the same melanocyte or melanoma cell line to reliably quantify the overlap." (PMID 32151278, 2020).
multiple myeloma (53 papers, 2013 to 2025). "For example, treatment of MM1.S myeloma cells with JQ1 (BRD4 inhibitor) leads to preferential loss of BRD4 at SEs and selective inhibition of SE-driven MYC transcription." (PMID 35740532, 2022). "Several recent studies have implicated BRD4 in the development of experimental models of sepsis, multiple myeloma, and chronic kidney disease." (PMID 29343723, 2018). "Since then BRD4 has been implicated in multiple myeloma as well as MYC driven tumors such as AML and neuroblastoma." (PMID 24796395, 2014). "A separate study of multiple myeloma found that MYC-associated SEs were occupied by remarkably high amounts of the coactivator bromodomain containing 4 (BRD4), a protein involved in the recruitment of elongation factors and binding of Mediator, as well as acetylated histones." (PMID 40265369, 2025). "Interestingly, the treatment of multiple myeloma cells with the anticancer BRD4 inhibitor JQ1 resulted in the preferential loss of BRD4 at the SE, prompting transcriptional elongation defects that preferentially affect genes with SEs, such as MYC oncogene." (PMID 36960780, 2023). "The treatment of multiple myeloma cells with the BRD4 inhibitor JQ1 resulted in the loss of BRD4 at the majority (90%) of promoters and more than half (60%) of the enhancer regions with a preferential loss of BRD4 at super-enhancers of key oncogenic drivers such as c-MYC." (PMID 34333666, 2021). "In the attempt of defining the molecular mechanisms beyond the cancer cytotoxicity of BETi in Multiple Myeloma (MM), Loven and colleagues showed that BRD4, together with Mediator, and P-TEFb is heavily accumulated on SEs and that BETi causes a preferential loss of BRD4 at these elements." (PMID 30466442, 2018). "Selective inhibition has differential effects: BRD4 inhibition alone suppresses tumor growth in multiple myeloma, AML, and solid tumors, whereas dual BRD2/BRD4 inhibition is often required in resistant models." (PMID 41583469, 2025). "In multiple myeloma (MM), BRD4 and mediators occupy large regions covered by SEs and drive the expression of signature genes, such as the Myc oncogene." (PMID 37501079, 2023). "Treatment of myeloma cells with JQ1 resulted in the selective deletion of BRD4 on SEs and revealed the presence of SE-related genes in MM cells." (PMID 37501079, 2023). "I-BET151 inhibits the release of IL-1β, and IL-6 in peripheral blood mononuclear cells and myeloma cells by reducing BRD4-mediated activation of NF-κB." (PMID 34540687, 2021). "For example, miR-338-3p expression is significantly reduced in multiple myeloma, and miR-338-3p can target BRD4 to suppress cell growth and migration, and facilitate apoptosis." (PMID 34889689, 2021). "I-BET151 targets BRD4 in multiple myeloma cells and inhibits the expression of C-MYC and IRF4, thereby improving the transcription and translation levels of MICA, promoting the degranulation of NK cells and inducing anti-tumor immune response." (PMID 34540687, 2021). "Similar results were obtained in AML and multiple myeloma, which depended on the BRD4-Myc axis to inhibit cell proliferation in vitro and in vivo through regulation by ARV-825." (PMID 33888130, 2021). "LncRNA H19 via sponging miR-152-3p up-regulates the expression of BRD4, thereby promoting the malignant behavior of multiple myeloma cells." (PMID 34324544, 2021). "It has been also shown that BI-2536 strongly inhibits BRD4-dependent expression of c-Myc in multiple myeloma cells in a similarly way to the bromodomain inhibitor JQ127." (PMID 29476067, 2018). "Since stable BRD4 depletion is cytotoxic for myeloma cells, in these experiments were used transient infections." (PMID 27903272, 2016). "Recently, a small-molecule inhibitor of BET bromodomains, JQ1, with high affinity for the first bromodomain of Brd4, has received much attention for its therapeutic potential against multiple myeloma and other cancer types that are addicted to the c-Myc oncogene." (PMID 24194944, 2013).
multiple myeloma (continued). "Indeed, the sensitivity of some multiple myelomas to JQ1 arises in part from a similar loss of Myc expression in cases where translocated MYCC coding sequences are juxtaposed to the IgH enhancer, which also binds BRD4." (PMID 26036281, 2015). "In multiple myeloma, circ-CCT3 binds miR-223-3p, attenuating the miR-223-3p-mediated repression of bromodomain containing 4 (BRD4) to sensitize cells to bortezomib treatment." (PMID 41153715, 2025). "It has shown preclinical antitumor activity across AML, multiple myeloma, and solid tumor models through BET/BRD4 blockade and MYC-axis suppression." (PMID 41335282, 2025). "JQ1 displacement of BRD4 from the MYC promoter/enhancer also led to suppression of MYC-driven malignancies, such as multiple myeloma and acute myeloid leukemia." (PMID 31824865, 2019). "Inhibition of the BRD4 bromodomains with JQ1 downregulates MYC mRNA transcription and leads to G1 cell cycle arrest in diverse tumor types, such as multiple myeloma." (PMID 26284497, 2015). "Recent reports describe a role for several members of the bromodomain and extraterminal (BET) protein family, including bromodomain-containing proteins BRD2, BRD3 and BRD4, in the maintenance of aberrant chromatin states in AML, ALL, myeloma and lymphoma." (PMID 25989842, 2015). "Furthermore, transcription of c-Myc, controlled by the epigenetic regulator, BRD4, and inhibition of BRD4 by the small molecule inhibitor, JQ1, showed potent anti-cancer activity in vitro and in vivo of several cancers, for example, multiple myeloma, AML and Burkitt’s lymphoma." (PMID 32098189, 2020).
lung carcinoma (51 papers, 2013 to 2026). "BRD4 is a well-known tumour-associated gene, and its upregulation is closely related to the development of various cancers, including lung cancer." (PMID 38229152, 2024). "More importantly, they demonstrated that high BRD4 expression was associated with a poor prognosis for patients with lung cancer." (PMID 35371325, 2022). "In addition, they detected that BRD4 overexpression was associated to histological type and malignant behaviors (lymph node metastasis, tumor differentiation, and stage) of lung cancer." (PMID 35371325, 2022). "A novel style of versatile nano‐proteolysis targeting chimera is constructed by the incorporation of the BRD4 degrader dBET6, which aims to target both lung cancer cells and M2 tumor‐associated macrophages (TAMs) which favors the tumor‐promoting microenvironment." (PMID 35988145, 2022). "Although BRDT and BRD4 expression levels are uncorrelated in lung cancer cell lines, the potential relationship between expression of full-length versus short BRD4 and BRDT isoforms is unclear." (PMID 40085698, 2025). "This includes expression of bromodomain-containing protein 4 (Brd4), which maintains active lung cancer cells." (PMID 41459064, 2025). "Characterization confirmed the nanoparticles’ stability, high drug-loading capacity, and triggerable drug release under acidic and reducing conditions, resulting in enhanced BRD4 degradation, caspase-3 activation, and apoptosis in lung cancer cells." (PMID 40284496, 2025). "Dual-luciferase reporter assay was performed to examine the interaction of the AL139294.1–miR-204-5p–BRD4 axis in lung cancer." (PMID 38229152, 2024). "On the contrary, the mRNA expression of BRD4 was higher in lung cancer tissues than in normal tissues, with an AUC value of 0.826 to discriminate LUAD tissues from normal tissues." (PMID 38229152, 2024). "BRD4 mRNA was positively correlated with Wnt5a and NF-κB2 mRNAs in lung cancer tissues in the TCGA cohort." (PMID 38229152, 2024). "Altogether, these results suggest that miR-204-5p targets BRD4 to inhibit the proliferative, migratory, invasive, and colony-forming abilities of lung cancer cells." (PMID 38229152, 2024). "The pH/GSH responsiveness of the nanosystem promoted intracellular release of dBET6, leading to BRD4 degradation, lung cancer cells and TAMs apoptosis, TME modulation, and subcutaneous and orthotopic lung tumor growth inhibition." (PMID 37984863, 2024). "Altogether, these results suggest that dysregulated miR-204-5p and BRD4 are involved in the development of lung cancer." (PMID 38229152, 2024). "Frequent ARID1A (the AT-rich interactive domain 1A [SWI-like] gene) depletion, detected in 20% of all lung cancers, induced chromatin remodeling and glycolysis, inhibiting cell death induced by the BRD4 inhibitor JQ1." (PMID 35831279, 2022). "The depletion of METTL3 inhibits tumorigenicity and sensitizes lung cancer cells to bromodomain-containing protein 4 (BRD4) inhibition." (PMID 36553648, 2022). "We identified BRD4 as a potential factor positively modulating KEAP1 expression at the transcriptional level in lung cancer." (PMID 35453346, 2022). "Specific degradation of BRD4 leads to substantial cell apoptosis of both lung cancer cells and TAMs, thereby remodeling the tumor microenvironment, which in turn, renders tumor shrinkage." (PMID 35988145, 2022). "It has also been reported that METTL3 can promote translation of a large subset of oncogenic mRNAs, and METTL3 depletion can inhibit tumorigenesis and sensitize lung cancer cells to BRD4 inhibition." (PMID 35794583, 2022). "Our findings suggest a novel strategy for lung cancer therapy involving engineered cell membranes to efficiently deliver the BRD4 PROTAC for the dual‐targeting of cancer cells and TAMs." (PMID 35988145, 2022). "Herein, bioinformatic analysis suggests bromodomain-containing protein 4 (BRD4) as a potential top transcriptional regulator of KEAP1 in lung cancer." (PMID 35453346, 2022).